MED23 (mediator complex subunit 23)
Description:
Required for transcriptional activation subsequent to the assembly of the pre-initiation complex (By similarity). Component of the Mediator complex, a coactivator involved in the regulated transcription of nearly all RNA polymerase II-dependent genes. Mediator functions as a bridge to convey information from gene-specific regulatory proteins to the basal RNA polymerase II transcription machinery. Mediator is recruited to promoters by direct interactions with regulatory proteins and serves as a scaffold for the assembly of a functional pre-initiation complex with RNA polymerase II and the general transcription factors. Required for transcriptional activation by adenovirus E1A protein. Required for ELK1-dependent transcriptional activation in response to activated Ras signaling.
Synonyms: ARC130; DRIP130; CRSP3; SUR2; CRSP130; CRSP133; MRT18; SUR-2
Tractability: Small molecule: a structure with a bound ligand is known; a high-quality ligand is known. PROTAC: ubiquitination databases record sites on it; its protein half-life has been measured; a small molecule that binds it is known.
Target class: Transcription factor
Gene: Protein-coding gene on chromosome 6 (131,573,966 to 131,628,242, reverse strand). Ensembl gene ENSG00000112282.
Subcellular location: Nucleus
Subcellular location (Human Protein Atlas): Nucleoplasm; Vesicles
Pathways (Reactome):
Gene expression (Transcription): Generic Transcription Pathway; MLL4 and MLL3 complexes regulate expression of PPARG target genes in adipogenesis and hepatic steatosis
Developmental Biology: Transcriptional regulation of white adipocyte differentiation
Disease: RSV-host interactions
Metabolism: PPARA activates gene expression
Gene Ontology:
Molecular function: protein binding; transcription coactivator activity
Biological process: regulation of DNA-templated transcription; positive regulation of gene expression; positive regulation of transcription elongation by RNA polymerase II; positive regulation of transcription initiation by RNA polymerase II; regulation of transcription by RNA polymerase II; RNA polymerase II preinitiation complex assembly; transcription initiation at RNA polymerase II promoter
Cellular component: core mediator complex; nucleus; transcription regulator complex; nucleoplasm; mediator complex
Genetic constraint (gnomAD): Loss-of-function variants: 93 observed, 143.87 expected, observed/expected ratio (o/e) 0.65, 90% interval 0.55 to 0.77. The upper end of that interval is the gene's LOEUF score, 0.77, which puts it in group 3 of 6, group 1 being the genes least tolerant of losing a copy. Missense variants: 926 observed, 1,579.8 expected, observed/expected ratio (o/e) 0.59, 90% interval 0.55 to 0.62. Synonymous variants: 516 observed, 549.75 expected, observed/expected ratio (o/e) 0.94, 90% interval 0.87 to 1.01.
Gene-disease validity (ClinGen):
ClinGen rates the evidence that MED23 causes each of these diseases.
syndromic intellectual disability (autosomal recessive): Moderate. A intellectual disability that is part of a larger syndrome.
Homologues: Orthologues: macaque MED23 (99% identical), chimpanzee MED23 (99% identical), rabbit MED23 (98% identical), pig MED23 (98% identical), dog MED23 (97% identical), guinea pig MED23 (97% identical), rat Med23 (97% identical), mouse Med23 (96% identical), tropical clawed frog med23 (93% identical), zebrafish med23 (90% identical), Drosophila melanogaster MED23 (49% identical), Caenorhabditis elegans sur-2 (23% identical).
Diseases named in the same sentence as MED23 in open-access papers:
MED23 is named in the same sentence as 48 diseases in open-access papers, as found by Europe PMC text mining. Sharing a sentence is not in itself a finding about the gene and the disease. The quoted sentences say what the papers report.
Intellectual disability (9 papers, 2015 to 2025). "The mutations of Med23 are associated with several brain diseases including microcephaly, epilepsy and intellectual disability, but its biological roles in brain development and possible behavioral consequence have not been explored in the animal model." (PMID 40114018, 2025). "Earlier this year, a study investigated the macroscopic regulation of chromatin structure by a MED23 point mutation associated with intellectual disability." (PMID 37446021, 2023). "In recently reported cases, several missense mutations of MED23 were found to be associated with familial intellectual disabilities (IDs)." (PMID 37446021, 2023). "It is also interesting to note that mutations in Med23 have previously been associated with intellectual disability, in some cases with a predisposition to seizures." (PMID 31211786, 2019). "For example, mutations in MED12 and MED23 in humans cause intellectual disabilities, and MED13L mutations cause congenital heart defects." (PMID 26445504, 2015). "Interestingly, clinical genetic evidence has linked Med23 mutation or down-regulated expression to intellectual disability, refractory epilepsy and microcephaly, suggesting possible involvement in brain-development diseases." (PMID 40114018, 2025). "Mutations in the transcription cofactor Mediator Med23 subunit are often associated with intellectual disability and white matter defects, although the precise functions and mechanisms of Mediator in myelination remain unclear." (PMID 39402028, 2024). "Importantly, a missense mutation of Med23 has been reported in patients with intellectual disability and dysregulation of expression of immediate early gene JUN and FOS." (PMID 32850819, 2020). "MED23 deficiency causes the autosomal recessive Intellectual Disability (ID)." (PMID 30847200, 2019). "Med23 CKO mice display an impaired performance in the spatial memory, which is consistent with the known functions of adult hippocampal neurogenesis, and may be one of factors contributing to the intellectual disability associated with the missense mutation of Med23." (PMID 32850819, 2020).
breast carcinoma (6 papers, 2016 to 2022). "When missense variants were assessed, three further associations were observed for overall breast cancer (TMEM161A, SIPA1L1, ERCC2), and a further seven were observed for subtypes (RNF175, NCKAP1L, PHAX, SMARCA2, EML5, NTRK3, MED23)." (PMID 35884425, 2022). "Analysis of rare missense variants identified evidence of associations of TMEM161A, SIPA1L1, and ERCC2 with overall breast cancer, RNF175 and NCKAP1L with ER-positive disease, and SLC22A10, PHAX, SMARCA2, EML5, NTRK3, and MED23 with ER-negative disease." (PMID 35884425, 2022). "TBLR1 is another nuclear co-repressor not previously reported to be associated with breast cancer, and MED23 is a component of the mediator complex and a coactivator involved in regulated transcription." (PMID 29023534, 2017). "However, few studies have investigated the role of MED23 in breast cancer." (PMID 35672824, 2022). "The best putative candidates in this group were TMEM161A, ERCC2, and SIPA1L1 for overall breast cancer, RNF175 and NCKAP1L for ER-positive disease, and PHAX, SMARCA2, NTRK3, EML5, and MED23 for ER-negative disease." (PMID 35884425, 2022). "It has been shown that MED23 knock‐down promotes tumorigenicity and inhibits apoptosis through a decrease of BAX expression, yet conversely, MED24 knock‐down in breast carcinoma cells lead to diminished cell proliferation and DNA synthesis." (PMID 38831555, 2020).
microcephaly (6 papers, 2019 to 2025). A congenital or acquired developmental disorder in which the circumference of the head is smaller than normal for the person's age and sex. "Although global development delay and microcephaly are common features for patients with Med23 mutations, the role of Med23 in brain development and other development-associated diseases was not well clarified." (PMID 40114018, 2025). "After reporting an additional novel case, we highlight ID, developmental delay, hypotonia, and microcephaly as potential clinical hallmarks of MED23 mutations owing to their repetitive appearance among diagnosed cases." (PMID 39144687, 2024). "Here we report an Iranian case with nonsyndromic ID presenting with developmental delay, microcephaly, hypotonia, severe ID, speech delay, and spasticity, who was homozygous for the novel MED23 c.670C>G variant." (PMID 30847200, 2019). "However, the neurodevelopmental disorders caused by MED23 mutations in patients, including microcephaly and global developmental delay, appear to be more severe than those in Med23Q649R mice." (PMID 39402028, 2024). "According to descriptions of further cases, the phenotype may be more complicated depending on the kind, location, and effect of MED23 mutations, whereas the ‘classical phenotype’ is defined as having characteristics such as microcephaly, axial hypotonia, epilepsy, dystonia, and spasticity." (PMID 39144687, 2024). "More data, however, are required to confirm the postnatal microcephaly as a key feature of MED23-related disorder." (PMID 36824420, 2023). "A retrospective assessment of the previously reported clinical data for these subjects confirms the occurrence of postnatal progressive microcephaly as a previously unappreciated feature of the phenotype of MED23-related disorder." (PMID 36824420, 2023). "In addition, our data suggest the occurrence postnatal microcephaly that may possibly be considered in the MED23-related disorders." (PMID 36824420, 2023). "Progressive microcephaly had never been reported in subjects with MED23 mutations, and thus, we speculate on the possibility of the occurrence of this feature in the disorders." (PMID 36824420, 2023).
lung carcinoma (5 papers, 2018 to 2025). "In this study, we utilized well-characterized models of lung adenocarcinoma that recapitulate human lung cancer through the activation of a KrasG12D allele to investigate the role of MED23 in lung cancer." (PMID 38195889, 2024). "For patient P03, the ImmuniT platform also uncovered two novel neoantigens, MED23 and SNTB2, both implicated in lung cancer progression." (PMID 41012124, 2025). "We previously found that Mediator complex subunit 23 (MED23) is important for the tumourigenicity of lung cancer cells with hyperactive Ras activity in vitro, although the in vivo function of MED23 in lung tumourigenesis remains to be explored." (PMID 38195889, 2024). "We previously demonstrated that MED23 and its binding partner ELK1 were selectively important for the proliferation and tumorigenicity of lung cancer cell lines with RAS mutations." (PMID 38195889, 2024). "Utilizing tissue microarrays to analyze 80 clinical samples of lung cancer, we previously found that nearly 85% of the lung cancer samples had significantly higher expression of MED23 than did normal tissue samples." (PMID 38195889, 2024). "In this study, we utilized well-characterized KrasG12D-driven non-small cell lung cancer mouse model to investigate the role of MED23 in lung cancer." (PMID 38195889, 2024). "Taken together, our data indicate that MED23 may also act as a tumor suppressor in Kras-induced lung cancer in vivo." (PMID 38195889, 2024). "Our previous study found that MED23 could selectively support the cell growth and tumorigenesis of lung cancer cell lines with mutant KRAS in vitro." (PMID 38195889, 2024). "Our previous study showed that MED23 was required for Ras-driven lung cancer in vitro." (PMID 38195889, 2024). "We then further analyzed the lung cancer samples collected in the TCGA database through relevant websites and found that there were indeed some patients with relatively low MED23 expression or even MED23 deletion." (PMID 38195889, 2024). "Lastly, since Med23 deficiency in mice is apparently important for the growth of non-small cell lung cancer, we examined whether there were also lung cancer patients with Med23 downregulation or deletion." (PMID 38195889, 2024). "In the future, drugs targeting MED23 combined with immunotherapy may specifically benefit patients with lung cancer with relatively low MED23 expression." (PMID 38195889, 2024). "To investigate the role of Med23 in lung cancer, we constructed a conditional Med23-knockout mouse model (Med23f/f), in which Med23 deletion in a small percentage of pulmonary cells was achieved by intranasal delivery of adenoviral Cre recombinase (Adeno Cre) when the mice were 6–8 weeks old." (PMID 38195889, 2024). "Collectively, these results indicate that there is indeed a small fraction of patients with low MED23 expression in the clinic and that our research may provide a new classification for lung cancer patients." (PMID 38195889, 2024). "Collectively, these findings revealed that MED23 may negatively regulate Kras-induced lung tumourigenesis in vivo, which would improve the precise classification of KRAS-mutant lung cancer patients and provide new insights for clinical interventions." (PMID 38195889, 2024).
viral infection (4 papers, 2013 to 2025). "Collectively, these findings indicate that Med23 deficiency leads to increased production of type I interferons and innate cytokines in response to viral infection, thereby inhibiting viral replication." (PMID 40705824, 2025). "This study revealed that Med23 is essential for viral infection and the suppression of host innate immunity, suggesting that it could serve as a potential target for the development of antiviral therapeutics." (PMID 40705824, 2025). "Med1 and Med23 bound the viral genome with an almost identical pattern, indicating they are parts of the Mediator complex bound early during viral infection." (PMID 31638576, 2019). "As IFN-λ expression is induced following activation of pathogen recognition receptors (PRRs) by virus infection, we tested whether Med23 induced IFN-λ by directly interacting with an interferon-responsive transcription factor (IRF)." (PMID 23950709, 2013). "Notably, prior research has shown that Foxo3 protein undergoes stress-induced degradation, raising the possibility that viral infection may disrupt the Med23-Foxo3 interaction." (PMID 40705824, 2025). "Collectively, these findings elucidate a previously unrecognized role of Med23 as a gatekeeper of the RIG-I-mediated antiviral innate immune response and suggest a potential target for controlling viral infection." (PMID 40705824, 2025). "Our data showed that Med23 transcriptionally regulates RIG-I expression, restoring IFN-I signaling following viral infection." (PMID 40705824, 2025). "In the absence of viral infection, Med23 knockout did not affect the lung tissue of the mice." (PMID 40705824, 2025).
developmental delay (3 papers, 2019 to 2024). "Moreover, we present a novel case, the first to be reported from Saudi Arabia, carrying a mutation in the MED23 gene, clinically presenting with seizure and developmental delay and diagnosed using advanced genetic testing." (PMID 39144687, 2024).
melanoma (3 papers, 2018 to 2025). A malignant, usually aggressive tumor composed of atypical, neoplastic melanocytes. "WT and Med23−/− mice were inoculated with B16F10 melanoma cells and intravenously injected with 2 μg of mock or α-GalCer three times (on days 0, 4, and 8), after which the number of lung metastases was counted." (PMID 30250136, 2018).
epilepsy (2 papers, 2023 to 2025). A brain disorder characterized by episodes of abnormally increased neuronal discharge resulting in transient episodes of sensory or motor neurological dysfunction, or psychic dysfunction. "Biallelic loss-of-function variants in MED23 cause a recessive syndromic intellectual disability condition with or without epilepsy (MRT18)." (PMID 36824420, 2023).
Hepatic fibrosis (2 papers, 2019 to 2025). The presence of excessive fibrous connective tissue in the liver. "In a Ccl4-induced hepatic fibrosis murine model, specific knockout of MED23 in stem cells resulted in exacerbated liver fibrosis, accompanied by increased chemokine production and inflammatory infiltration." (PMID 40940746, 2025). "Compared with their control littermates, mice with hepatic Med23 deletion exhibited aggravated carbon tetrachloride (CCl4)-induced liver fibrosis, with enhanced chemokine production and inflammatory infiltration as well as increased hepatocyte regeneration." (PMID 31805036, 2019). "Here, we show that the transcriptional Mediator complex subunit 23 (MED23) participates in the development of experimental liver fibrosis." (PMID 31805036, 2019). "Both the comprehensive transcriptome analysis and in vitro assays indicate that RORα, one member of the ROR family, is the partner of MED23 in the pathogenesis of liver fibrosis." (PMID 31805036, 2019). "Collectively, these data suggest that the ablation of Med23 in hepatocytes renders mice prone to liver fibrosis." (PMID 31805036, 2019). "Similar to the CCl4-induced fibrosis model, Med23 silencing also resulted in increasing mRNAs related to liver fibrosis, including Col1a1, Col3a1, Tgfβ1, Pdgfβ, Tgfβr1, Pdgfrβ, and Timp1." (PMID 31805036, 2019). "This study reveals that the transcriptional Mediator subunit MED23 regulates the pathogenesis of liver fibrosis by controlling the production of inflammatory cytokines such as CCL5 and CXCL10." (PMID 31805036, 2019). "We observed that mice with hepatocyte-specific Med23 deletion show enhanced liver fibrosis." (PMID 31805036, 2019). "However, in our study, although ECM deposition and liver fibrosis increased after hepatocyte-specific Med23 deletion, we further observed increased compensatory hepatocyte proliferation in med23Δli mice compared with that in control mice." (PMID 31805036, 2019). "Importantly we observed that there was an increase in α-SMA+ cells as well as protein level of Col1a1 in Med23-deficient mouse livers, suggesting that Med23 ablation can also promote MCD diet–induced liver fibrosis." (PMID 31805036, 2019). "Thus, mice with Med23 deletion in hepatocytes seem to be able to mount augmented immune responses to chronic CCl4 administration, which possibly results in enhanced liver fibrosis and increased compensatory hepatocyte proliferation." (PMID 31805036, 2019). "In conclusion, we demonstrate for the first time that the Mediator subunit MED23 plays an important role in experimental liver fibrosis and provide new insight into the molecular mechanisms of inflammatory responses that initiate fibrotic changes upon liver injury." (PMID 31805036, 2019). "In the future, targeting the MED23/chemokine axis may provide intervention strategies for liver fibrosis." (PMID 31805036, 2019). "Collectively, these findings reveal hepatic MED23 as a key modulator of chemokine production and inflammatory responses and define the MED23-CCL5/CXCL10 axis as a potential target for clinical intervention in liver fibrosis." (PMID 31805036, 2019). "Mechanistically, the orphan nuclear receptor RAR-related orphan receptor alpha (RORα) activates the expression of the liver fibrosis-related chemokines C-C motif chemokine ligand 5 (CCL5) and C-X-C motif chemokine ligand 10 (CXCL10), which is suppressed by the Mediator subunit MED23." (PMID 31805036, 2019). "Our study demonstrated that hepatic RORα, in cooperation with MED23, plays a role in inflammatory responses, acting as a positive regulator of CCL5 and CXCL10 in initiating the liver fibrosis, which suggests new molecular targets for clinical intervention in liver fibrosis." (PMID 31805036, 2019).
hepatocellular carcinoma (2 papers, 2022 to 2025). A malignant tumor that arises from hepatocytes. "Overexpression of MED23 was confirmed to promote tumorigenesis in NSCLC and hepatocellular carcinoma." (PMID 35672824, 2022).